TOMM6 (translocase of outer mitochondrial membrane 6)
Description:
Component of the translocase of the outer membrane of mitochondria (TOM) complex essential for the recognition and translocation of cytosolically synthesized mitochondrial preproteins. The TOM complex associates with the ion channel VDAC2 and PINK1 kinase at depolarized mitochondria, this interaction stabilizes PINK1 at the outer mitochondrial membrane and triggers downstream mitophagy by the recruitment of the E3 ubiquitin ligase PRKN.
Synonyms: OBTP; TOM6
Tractability: Small molecule: a structure with a bound ligand is known. PROTAC: its protein half-life has been measured.
Gene: Protein-coding gene on chromosome 6 (41,787,652 to 41,790,064, forward strand). Ensembl gene ENSG00000214736.
Subcellular location: Mitochondrion outer membrane
Subcellular location (Human Protein Atlas): Mitochondria
Pathways (Reactome):
Autophagy: PINK1-PRKN Mediated Mitophagy
Protein localization: Mitochondrial protein import
Gene Ontology:
Molecular function: protein binding
Biological process: protein insertion into mitochondrial outer membrane
Cellular component: mitochondrion; mitochondrial outer membrane; TOM complex; mitochondrial outer membrane translocase complex
Genetic constraint (gnomAD): Loss-of-function variants: 6 observed, 6.39 expected, observed/expected ratio (o/e) 0.94, 90% interval 0.51 to 1.72. That is too few expected variants to judge how well the gene tolerates losing a copy. Missense variants: 104 observed, 102.22 expected, observed/expected ratio (o/e) 1.02, 90% interval 0.87 to 1.2. Synonymous variants: 44 observed, 39.44 expected, observed/expected ratio (o/e) 1.12, 90% interval 0.88 to 1.43.
Homologues: Orthologues: chimpanzee TOMM6 (100% identical), guinea pig TOMM6 (96% identical), dog TOMM6 (93% identical), mouse Tomm6 (91% identical), rabbit TOMM6 (91% identical), tropical clawed frog tomm6 (55% identical), zebrafish tomm6 (49% identical).
Diseases named in the same sentence as TOMM6 in open-access papers:
TOMM6 is named in the same sentence as 7 diseases in open-access papers, as found by Europe PMC text mining. Sharing a sentence is not in itself a finding about the gene and the disease. The quoted sentences say what the papers report.
tumor (1 paper, 2025). "CYP20A1 and TOMM6 influence tumor metabolism and response to stress." (PMID 40867248, 2025). "TOMM6 plays a role in mitochondrial function, supporting metabolic adaptations in tumor cells." (PMID 40867248, 2025).
TOMM6 also shares sentences with these, for which no sentence is quoted: Alzheimer disease (1 paper); cancer (1); colon cancer (1); infection (1); prostate carcinoma (1); testis cancer (1).